LAG3 (lymphocyte activating 3)
Diseases named in the same sentence as LAG3 in open-access papers (continued):
Sharing a sentence is not in itself a finding about the gene and the disease.
tumor (continued). "LGALS3 expression showed a significant positive association with CD274, TIGIT, PDCD1, HAVCR2, CTLA4, LAG3, as well as PDCD1LG2 after adjustment for tumor purity in HCC." (PMID 38643145, 2024). "In particular, in the prostate cancer model, combined blockade of PD-1 and LAG-3 with vaccination resulted in a significant anti-tumour effect." (PMID 38660136, 2024). "CD8+ T cells in cluster 7, the majority of which was localized in the tumour, additionally expressed LAG-3." (PMID 38986249, 2024). "The common immune checkpoints include CTLA-4, LAG-3 and PD-1, all of which are widely distributed in solid tumors and have a critical function in the tumor microenvironment (TME)." (PMID 38571495, 2024). "Tumor-bearing mice were divided into monotherapy treatment groups to receive 200 μg injections of anti-PD-1, anti-LAG-3, or anti-TIM-3 mAbs, or IgG isotype control." (PMID 39623404, 2024). "Gal-3 has been reported to mediate anti-tumor immune responses by inhibiting CD8+ T cells with LAG-3 and inhibiting the expansion of plasmacytoid dendritic cells." (PMID 39252941, 2024). "LAG-3 is expressed on the cell membranes of tumor-infiltrating lymphocytes (TILs), activated CD4+ and CD8+ T cells, and regulatory T cells (Tregs), where it binds to MHC-II molecules on antigen-presenting cells." (PMID 39743998, 2024). "Fibrinogen-like protein 1 (FGL1), a ligand of the inhibitory receptor LAG-3, can induce LAG-3 clustering and has recently been considered a checkpoint for tumor immunotherapy." (PMID 38973608, 2024). "LAG3 exhibited remarkable discriminatory potential in distinguishing tumor tissue from normal tissue, as demonstrated by an impressive area under the curve (AUC) of 0.854 (95% confidence interval (CI): 0.874–0.939)." (PMID 38277212, 2024). "FGL-1 secreted by tumor cells within the TME can bind to LAG-3 on TILs, thereby inhibiting the anti-tumor activity." (PMID 39660130, 2024). "In order to shed light on this question, a 4-gene inflammatory signature comprised of CD8A, STAT1, LAG3, and CD274 (encoding PD-L1) was assessed by the RNA-sequencing of the baseline tumor samples of patients included in the CheckMate-816 study." (PMID 39123401, 2024). "CBLB was brought up among more than 100 ubiquitin-related target genes in lymphoid infiltration, and it was found to be among the top E3 ubiquitin ligases co-expressed with PDCD1 and LAG3 in the tumor microenvironment (Dataset EV3)." (PMID 39030301, 2024). "This impairment of T cell-mediated anti-tumor immune responses suggests that LAG-3 expression levels in different cancer types correlate with clinical outcomes, thereby highlighting its potential as a predictive biomarker." (PMID 39660130, 2024). "LAG3 is often co-expressed and upregulated on TILs along with PD-1, contributing to immune exhaustion and facilitating tumor growth." (PMID 38617537, 2024). "It was discovered that LAG-3 was co-expressed with PD-1, and this co-expression was predominantly found on PD-1+ T cells within the tumor." (PMID 38390331, 2024). "The LAG-3 pathway has thus now been established as the third immune checkpoint pathway that can be inhibited to stimulate anti-tumor immune responses with clinical benefit." (PMID 38773064, 2024). "Preclinical and clinical studies have shown that LAG-3 inhibitors can restore T cell function and enhance anti-tumor immunity, particularly in combination with other ICIs." (PMID 39743998, 2024). "Currently, the primary mechanisms of regressive tumor effects are PD-1 and, more recently, additional pathways such as Lag-3, TIGIT, and Tim-3, which directly target and reinvigorate Tex cells." (PMID 38460046, 2024). "Research has demonstrated that anti-LAG-3 therapy can improve T cell proliferation, rejuvenate exhausted cytotoxic T lymphocytes, and increase tumour infiltration in murine cancer models." (PMID 39337605, 2024).
tumor (continued). "Other studies have reported that the cleavage of membrane LAG3 is required for T cell proliferation, and the induction of an anti-tumor response upon anti-PD-1 treatment." (PMID 38822401, 2024). "Blockade of the FGL1/LAG-3 interaction by anti-FGL1 mAb or anti–LAG-3 mAb enhances antitumor immunity and shows therapeutic effects on an established mouse subcutaneous tumor model of the MC38 cell line." (PMID 38973608, 2024). "Both intratumoral CPMV therapy and LAG-3 inhibition act on a multiple immune cell types and pathways to promote an anti-tumor immune response." (PMID 38349406, 2024). "Preclinical studies assessed the effect of inhibiting LAG-3 function on tumor progression by blocking the interaction between LAG-3 and its ligand using mAbs." (PMID 39660130, 2024). "This suggests that the expression level of LAG3 holds valuable reference significance in the selection of anti-tumor drugs." (PMID 38277212, 2024). "This analysis showed that the presence of UPP1high tumor cells was significantly positively associated with FOXP3+ regulatory T cells (Tregs), MMP11+ cancer-associated fibroblasts (CAFs), LAG3 + PDCD1 + CD8+ exhausted T cells, and M2-like SPP1+ macrophages." (PMID 38331898, 2024). "Blocking LAG-3 can restore NK cell-mediated cytotoxicity against tumor cells as well as the function of exhausted T cells and enhance anti-tumor immunity." (PMID 38349406, 2024). "These infiltrating CD8+ lymphocytes have been primarily associated with inactivity and exhaustion given their constant exposure to tumor antigens and their high expression of inhibitory receptors such as PD-1, LAG-3, TIGIT, and CD39 46-48." (PMID 38250045, 2024). "In vivo treatment of tumor-bearing mice with MHC-II-blocking anti-Lag-3 (aLag-3) Ab resulted in reduced tumor size similar to anti-PD-1 (aPD-1) Ab." (PMID 39234253, 2024). "The binding of FGL1 and LAG-3 inhibits antigen-specific T cell immune response, and blocking the interaction between FGL1 and LAG-3 can reactivate the anti-tumor immune ability of T cells." (PMID 38177102, 2024). "Despite ligands expression on U266 and MM1.s tumor cells, LAG-3 disruption didn’t appear to impact on TCRED function in these assays." (PMID 38510235, 2024). "Two potential ligands have been identified for LAG-3, which are present in the tumor microenvironment: liver sinusoidal endothelial cell lectin (LSECtin) and galectin-3 (Gal-3)." (PMID 39125946, 2024). "We also examined how CPMV IIT combination treatment altered the tumor microenvironment with respect to LAG-3 expression." (PMID 38349406, 2024). "Excluding MHC-II, the binding mechanism of other ligands to LAG-3 and the function of tumor immunity still need to be elucidated." (PMID 39660130, 2024). "The connection of Gal-3 and LAG-3 is an important mechanism in suppressing tumor-specific CD8+ T cells." (PMID 39125946, 2024). "Overall, it included more than 12000 TCGA samples and established the relationships between PDCD1/LAG3 gene expression with immune cell infiltration and an extensive number of biomarkers within the tumor-immune infiltrate." (PMID 39030301, 2024). "Relatlimab can bind to the LAG-3 receptor which blocks the interaction between LAG-3 and its ligand to reduce LAG-3 pathway-mediated immunosuppression and promote T-cell proliferation, inducing tumor cell death." (PMID 38269271, 2024). "Upregulation of LAG-3 has been reported in various malignancies, including AML, and is associated with T cell dysfunction and tumor immune evasion." (PMID 38792904, 2024). "The expression of LAG-3 is negatively correlated with the immune regulatory function of specific T cells, and inhibiting LAG-3 function can enhance the anti-tumor effect of specific CD8+ T cells." (PMID 38724599, 2024). "In comparison to PD-1+LAG-3- cells, PD-1+LAG-3+ T cells within the tumor exhibited a diminished ability to generate cytokines, including IL-2 and IFN-γ, as well as granules such as perforin (PFN) and granzyme B (GzmB)." (PMID 38390331, 2024).
tumor (continued). "When analyzing distinct markers among LAG-3 + B cells, we observed that most of these cells in the spleen and tDLNs had IgD expression for both control and tumor-bearing mice, accounting for ≥ 90% of CD19 + LAG-3 + cells." (PMID 38773133, 2024). "The potential of LAG-3 to predict anti-PD-1 therapy response has been investigated, which found a strong correlation between tumor-infiltrated LAG-3 expression and therapy resistance." (PMID 38673829, 2024). "ICIs involves mainly CTLA-4, PD-1, PD-L1 or LAG-3 blocking agents that reactivates the immune system against tumour cells." (PMID 38322766, 2024). "This pathway is expressed in tumour-associated macrophages and CAF, leading to the upregulation of PDL1 expression in tumoural cells along with an increase in Lymphocyte-activation gene 3 (LAG3), conferring resistance to anti-PDL1-based therapies." (PMID 39430087, 2024). "Studies have indicated that the high expression of LAG-3/PD-L1 in tumor tissue results in lower survival rates among patients with DLBCL." (PMID 38627681, 2024). "Immunosuppressive molecules, such as PD‐L1, CTLA‐4, TIM‐3, BTLA, CD160, LAG3, and 2B4,73 not only dampen the tumor's immune response but also impact the efficacy of OVs in infecting tumor cells." (PMID 39399642, 2024). "Presently, a clinical study has explored the inhibitory effects of LAG-3 and PD-1 within the tumor microenvironment of metastatic TNBCs." (PMID 38397971, 2024). "The high MMrisk group was positively correlated with B cells, plasma cells, CD4 memory cells, Mast cells, CAFs, monocytes, M2 macrophages, Endothelial, tumor mutation, and most immune checkpoints (PD1, Tim-3, CTLA4, LAG3)." (PMID 38890346, 2024). "In mouse cancer models, the concurrent blockade of PD-1 and LAG-3 led to tumor regression in the majority of mice with increased survival." (PMID 39534873, 2024). "Upon 99mTc-labeling, anti-hLAG-3 Nb 3187 and anti-mLAG-3 Nbs 3206 and 3132 demonstrated specific tumor uptake in LAG-3-overexpressing tumor-bearing mice." (PMID 39281708, 2024). "Research indicates that simultaneous blockade of LAG‐3 and PD‐1 is more effective in restoring immune homeostasis and enhancing tumor immunity than targeting either checkpoint alone." (PMID 39415846, 2024). "The results demonstrate that most anti-tumor drugs, including sorafenib, exhibit higher drug sensitivity in the LAG3 low-expression group." (PMID 38277212, 2024). "The detailed characterization of the T cell populations revealed the expression of a further immune checkpoint, namely LAG-3, on the majority of T cells, possibly impairing their activation after binding to tumor cell MHC II." (PMID 39075115, 2024). "Median follow-up was 49.4 months, 8.7% had acral cutaneous melanoma, 50% were BRAF-positive, 79.9% were LAG-3 positive, 26.1% were tumor PD-L1-positive and 6.5% received prior adjuvant therapy." (PMID 39727691, 2024). "This approval highlights LAG-3’s potential as a promising tumor immunotherapy target, succeeding PD-1 and CTLA-4." (PMID 38928150, 2024). "On tumor-infiltrating lymphocytes (TILs), LAG-3 and PD-1 are frequently co-expressed and elevated, which causes immune exhaustion and permits immune evasion by cancer cells." (PMID 39343796, 2024). "Evidence suggests that LAG-3 signaling negatively regulates the activation, proliferation, and cytokine secretion of Th1 cells, mechanisms exploited by tumor cells to evade immune surveillance during carcinogenesis and metastasis." (PMID 39684559, 2024). "The GEPIA database compared PDCD1 and LAG3 mRNA expression between AML tumor samples and healthy control samples from TCGA." (PMID 38792904, 2024). "T-cell exhaustion is a dysfunctional state that involves the upregulation of inhibitory receptors (e.g., PD-1, LAG3, and 2B4) in the early to middle stages, accompanied by reduced anti-tumor function." (PMID 39650651, 2024).
tumor (continued). "Studies have indicated that margetuximab application leads to an upregulation of LAG-3/PD-L1 expression on immune cells, along with enhanced margetuximab-induced tumor lysis in the presence of tebotelimab." (PMID 38627681, 2024). "LAG-3 molecule negatively regulates T cells and plays a vital role in maintaining the homeostasis of the immune system and promoting tumor immune escape." (PMID 38919624, 2024). "In summary, the expression of PD-1, CTLA-4, LAG-3, TIM-3, and TIGIT ligands in tumor cells is associated with an adverse prognosis." (PMID 38893211, 2024). "Despite the promising safety profile and anti-tumor activity of LAG-3-targeted molecules in multiple clinical studies, their efficacy as monotherapy remains limited, making combination therapy a necessary approach." (PMID 39743998, 2024). "LAG3 inhibits T‐cell proliferation and activation, and is thought to play an important role in tumor immunity." (PMID 38234210, 2024). "Intratumorally infiltrated M28z and MBBz CAR T cells exhibited upregulation of PD-1 and LAG3 in response to antigens, while the respective ligands were expressed by MSLNþ-positive tumor cells." (PMID 38903506, 2024). "Immune checkpoint molecules such as programmed cell death protein 1 (PD-1) and lymphocyte activation gene-3 (LAG-3) are essential for controlling anti-tumor immune responses." (PMID 38792904, 2024). "LAG-3 along with PD-1 dual blockade have been shown in mouse models to improve anti-tumor immune response by increasing CD8+ tumor-infiltrating cells in the tumor microenvironment and decreasing T regulatory cells." (PMID 39199689, 2024). "By blocking LAG-3 signaling, T cell proliferation and effector functions are enhanced, improving anti-tumor immune responses." (PMID 39669560, 2024). "High levels of checkpoints PD‐1, PD‐L1, PD‐L2 and LAG‐3 were found in one to two tumours each; moderate levels of these checkpoints were found in additional cancers." (PMID 35866362, 2024). "Zhou and colleagues found that antibodies against TIM-3 or LAG-3 can repair the response of T cells to tumor antigens, and the combination of antibodies shows a superimposed effect." (PMID 39845973, 2024). "Although the assessment of LAG3 expression in KIRC was limited to 533 tumor samples and 72 adjacent normal tissue samples in the TIMER database, notable differences in LAG3 expression were observed between KIRC tumor tissues and normal tissues." (PMID 38277212, 2024). "Approved ICIs like cytotoxic T-lymphocyte antigen-4 (CTLA-4), programmed death-1 (PD-1), its ligand PD-L1, and lymphocyte activation gene-3 (LAG-3) have improved cancer patient outcomes by enhancing anti-tumor responses." (PMID 38375475, 2024). "FS-118 enhanced the bridging between T cells and tumor cells via the dual targeting of LAG-3 and PD-L1 in TME." (PMID 38257366, 2024). "Vaccination studies carried out in mice demonstrated that LAG3‐Ig enhanced immune responses and slowed tumor growth." (PMID 39560030, 2024). "IL-2 depletion enriched an exhaustion-prone subset of CD8+ TILs (cluster 11), characterized by CD44hiTcf1–TOX+Tim3+Lag3+PD-1+TIGIT+CD8+ in MC38 tumor–bearing KO mice." (PMID 38787791, 2024). "LAG-3 inhibitors have shown potential in restoring T cell functions and enhancing anti-tumor immunity, particularly when used in combination with existing ICIs." (PMID 39743998, 2024). "Further studies are needed to fully elucidate the mechanism of action of LAG-3 and optimize its application in tumor therapy." (PMID 39660130, 2024). "This is further affected by the expression of immune checkpoints like PD-1 and LAG-3 in these T cells, which inhibit effective immune response and facilitate tumor progression." (PMID 38474119, 2024). "In the TME, constant antigen exposure heightens LAG-3 expression, contributing to T cell exhaustion and impaired tumor cell elimination." (PMID 39726592, 2024).
tumor (continued). "LAG3 was a promising immune checkpoint, and overexpression of LAG3 promoted tumor cell development by forming an immunosuppressive microenvironment to suppress the activity of immune cells." (PMID 38604154, 2024). "LAG-3 interacts specifically with tumor cells and antigen-presenting cells (APCs) via the major histocompatibility complex class II (MHC-II), which triggers co-inhibitory signaling pathways and ultimately results in T cell alterations." (PMID 39594765, 2024). "Instead, they express the inhibitory receptors PD-1, Tim3, and LAG3 and lose their ability to kill tumor cells." (PMID 39768300, 2024). "The dissection of intracellular pathways that mediate the inhibitory effects of this receptor are a prerequisite for development of effective small compound inhibitors of LAG‐3 to enhance anti‐tumor responses in cancer patients." (PMID 39560030, 2024). "It is well known that the EBV+ DLBCL have a tolerogenic environment, characterized by the expression of PD1, TIM3, and LAG3 in tumor-infiltrating lymphocytes, and PDL1 in different types of cells, such as macrophages." (PMID 38280007, 2024). "In comparison with monotherapy, combined inhibition of LAG-3 and PD-1 increased full tumor regression in approximately 50% of Sa1N fibrosarcoma mice." (PMID 38898505, 2024). "ZGGS15 demonstrated a significant anti-tumor effect in the anti-PD-1 weak response model, outperforming single agents anti-LAG-3 or anti-TIGIT." (PMID 38724599, 2024). "An animal model consisting of tumor-bearing Msh2loxP/loxP;TgTg (Vil1-cre) mice treated with an anti-PD-1 and anti-LAG-3 combination showed reduced circulating Tregs and lower levels of Tex cells positive for CTLA-4, LAG-3, and PD-1." (PMID 39273452, 2024). "Lymphocyte activation gene 3 protein (LAG3) is an immune checkpoint receptor that is highly upregulated on exhausted T cells in the tumor microenvironment." (PMID 38556085, 2024). "In this report, we present the case of a patient with TNBC who experienced a complete tumor regression when treated with a combination of PD-1 and LAG-3 blocking antibodies." (PMID 38336861, 2024). "Treatment with the anti-LAG-3/PD-L1 mAb2 (bispecific antibody) eliminated tumors in six of eight mice and slowed tumor growth in the remaining two mice." (PMID 38581716, 2024). "There are also studies showing that CAR-T cells with blockade of CTLA-4 and LAG-3 exhibit stronger anti-tumor activity in various experimental animal models." (PMID 38571495, 2024). "Through the transient activation of T-cell-enriched cultures from TNBC-derived PBMCs, we have established that the NExT platform is naturally functionalized with the IC receptors PD1, TIM3, and LAG3 that can bind the cognate ligands on tumor cells." (PMID 38730475, 2024). "Instead, the association between peritumoral CD8+ cells and prognosis depended on the expression of the immune checkpoints (PD-1, LAG-3, PD-L1, and PD-L2) and the localization of dendritic cells in the tumor microenvironment." (PMID 38578213, 2024). "The cyan cluster consisted of 13 keywords, including TIM-3, CTLA-4, and PD-1, which exhibit comparable functionalities to LAG-3 and hold significant importance in autoimmune, tumor-immune, and anti-infective immune responses." (PMID 38390331, 2024). "Reducing FGL1 levels by oxysophocarpine or aspirin treatment sensitized HCC cells to anti–LAG-3 or anti–PD-L1 immunotherapy in the subcutaneous tumor model." (PMID 38973608, 2024). "For example, bispecific antibodies targeting LAG-3 and PD-1 have shown promise in enhancing anti-tumor responses through the activation of dendritic cells." (PMID 39336897, 2024). "Of potential clinical importance, elevated expression of ISG15 in the TME has been linked to higher histological grade, larger tumor size, a “stemmy” cancer phenotype, low CD8+ TIL content, expression of PD-L1/IDO-1/LAG-3, and poor clinical prognosis." (PMID 38312842, 2024).